MITF (melanocyte inducing transcription factor)
Diseases named in the same sentence as MITF in open-access papers (continued):
Sharing a sentence is not in itself a finding about the gene and the disease.
melanoma (continued). "In melanoma cells resistant to MAPK inhibitors including BRAFi, a state of low expressions of MITF and SOX10 could induce high levels of tyrosine kinase receptors, such as AXL receptor tyrosine kinase (AXL) and epidermal growth factor receptor (EGFR) that help to maintain the resistance." (PMID 32532957, 2020). "Interestingly, when we examined the relationship between MITF/AXL ratio and IL1B using 18 human melanoma cells without drug treatment, we found a strong inverse correlation between the MITF/AXL ratio and IL1B gene expression." (PMID 33396632, 2020). "After intersecting and analyzing both gene sets, we further found that most of the genes with a positive correlation with MITF expression in lung adenocarcinoma had a negative correlation with MITF in melanoma (354 genes out of 446 total genes; p = 1.01E−10, Chi-square test)." (PMID 33293474, 2020). "Interestingly, we could also observe in melanoma cells that NRF2 positively regulates EGFR and therefore strengthens the dedifferentiated phenotype by simultaneously suppressing MITF activity and inducing EGFR expression." (PMID 32978520, 2020). "Despite the relevance in melanoma progression, MITF is currently classified as a not-druggable target; therefore, modulating its upstream pathways, including CREB, could represent an alternative viable approach to control MITF activity in melanoma." (PMID 33126560, 2020). "Since MITF controls transcription, we first examined whether the mRNA expression of the key SDH subunit SDHB correlated with the pseudo‐hypoxic signature in the CCLE melanoma cell lines." (PMID 31207090, 2019). "In the investigated melanoma lesions NFATc2 expression showed an association with EMT-markers and lack of MITF, but at least one exception was found, in agreement with the notion that EMT and melanoma de-differentiation are multi-step processes with several intermediate phenotypic profiles." (PMID 30710146, 2019). "This is most likely because in melanoma invasion reflects in part a response to a low nutrient supply environment and that by promoting proliferation, for example by activating CDK2, MITF imposes a high nutrient demand state that is incompatible with nutrient limitation." (PMID 31207090, 2019). "MITF level and expression of MITF-dependent pigmentation-related genes, MLANA, PMEL, TYR, and DCT, in drug-naïve and vemurafenib- or trametinib-treated patient-derived melanoma cell lines and their drug-resistant counterparts were analysed and referred to genomic alterations." (PMID 31354817, 2019). "MITF-directed RNAi did not affect c-MYC mRNA expression in MITF-negative melanoma (A375) and non-melanocytic tumor cells (MCF7 breast cancer and U2OS osteosarcoma cells) in contrast to MITF-dependent 501 mel cells ruling out siRNA-mediated off-target effects on c-MYC." (PMID 30651597, 2019). "The dependence of TFIIH-CAK on sequence-specific MITF and c-MYC constitutes a previously unrecognized mechanism feeding into super-enhancer-driven or other oncogenic transcriptional circuitries, which supports the concept of a transcription-directed therapeutic intervention in melanoma." (PMID 30651597, 2019). "MITF and SOX10 co-occupy approximately 3,600 binding sites on chromatin in human melanoma cells, marking a subset of active regulatory elements that function to control key melanoma transcriptional programmes underpinning proliferation, invasion and metastasis." (PMID 31881017, 2019). "Additionally, we reported a GH-induced upregulation and GHRKD-induced suppression of MITF-regulated melanogenesis pathway genes—TYR, TYRP1, TYRP2/DCT—as well as melanosomal markers PMEL (gp100) and MLANA, in multiple melanoma cell lines, xenograft models, and in silico analyses." (PMID 31547367, 2019).
melanoma (continued). "Interestingly, both MITF and the lncRNA SAMMSON reside within this amplicon, suggesting that a proportion of melanoma patients alter oxidative metabolism through two unique independent mechanisms, the SAMMSON-p32 axis and the MITF-PGC1α axis, both of which are regulated by SOX10." (PMID 31416288, 2019). "Master transcription factors SOX10/MITF and AP-1/TEADS play a crucial role in the control of the proliferative and invasive transcriptional networks, respectively, while c-JUN, a component of AP-1, is a mediator of the mesenchymal-like profile of melanoma cells." (PMID 30710146, 2019). "Furthermore, cancer progression may employ altered phosphorylation of pivotal transcription factors, as has been suggested for MITF, PAX3, and β-catenin in melanoma." (PMID 29315345, 2018). "Thus, the situation appears to be more complex and simply dividing ‘aggressive’ and ‘non-aggressive’ melanomas by their MITF expression state is not sufficient." (PMID 29545604, 2018). "Consequently, melanomas resistant to BRAF/MEK inhibitors have increased mitochondria biogenesis and metabolically switch to oxidative phosphorylation (OXPHOS) through upregulation of MITF and PGC1α." (PMID 30651927, 2018). "Most recent explorations of the functional role of CD271 in melanoma have clearly demonstrated that CD271+ cells comprise a special subtype of melanoma cells with stem-like properties and a lower expression of melanocyte-markers such as MART1, MITF and tyrosinase." (PMID 30053879, 2018). "The results suggest that low levels of MITF may still maintain relatively high proliferation and might reflect, rather than cause, the EMT‐like changes occurring in melanoma." (PMID 29369499, 2018). "The growth rate data of low‐MITF cells (SK‐MEL‐2, Dor and A375) were completely mixed with the data of high‐MITF cell lines (MeWo, 501mel, SK‐MEL‐28), indicating that even low level of MITF can sustain high proliferation rate in some melanomas, apparently dependent on the cellular context." (PMID 29369499, 2018). "In line with YAP regulating MITF expression, we found that YAP depletion resulted in the reduced expression of MITF target genes, including not only differentiation but also proliferation markers, and indeed, melanoma cell proliferation was significantly reduced after YAP knockdown." (PMID 29545604, 2018). "Interestingly, in our setting, MITF downregulation at late PT was accompanied by increasing AXL expression, suggestive for a role of AXL in melanoma cells proliferation in the absence of MITF." (PMID 29614062, 2018). "In addition, high levels of miR-211 in melanoma-derived Exo were shown to indicate a reduced sensitivity to BRAF inhibitors, the mechanism of which involves the over-expression of MITF, a regulator of the TRPM1 gene, resulting in the prolonged survival of melanoma cells." (PMID 29755693, 2018). "Here we report the regulation of expression of the NFIB transcription factor by BRN2 in melanoma cells, which in turn acts to increase cell migration and potentially invasion through the positive and negative regulation of the epigenetic regulator EZH2 and MITF respectively." (PMID 28119061, 2017). "However, we failed to observe any difference in cell viability after treatment with phenformin between CTRL and MITF-overexpressing cells, indicating that MITF is not sufficient to rescue phenformin cytotoxic activity in melanoma cells." (PMID 28036292, 2017). "However, when we tested the effect of phenformin in MITF-overexpressing melanoma cells, we did not observe any difference in drug response in MITF- and CTRL-cells." (PMID 28036292, 2017). "Moreover, depletion of ATF4 using RNAi technology prevented the reduction in MITF expression in response to glucose restriction, clearly demonstrating that ATF4 acts as the link between glucose metabolism and MITF in melanoma cells." (PMID 28380427, 2017).
melanoma (continued). "However, the commercially available antibodies for MiTF are not specific for the melanocytic MiTF isoforms, and a uterine leiomyoma can be positive for melanoma markers including MiTF." (PMID 27998309, 2016). "It seems that a basal level of MITF expression is necessary for melanoma cells and therefore MITF expression and activity is not entirely down-regulated, which is in line with the observation that almost all melanoma cells maintain their ability to synthesize melanin." (PMID 26927636, 2016). "Similarly, miR-340 downregulation promotes melanoma progression through de-repression of drug transporters, RAS-RAF-MAPK signalling components and the key melanocytic transcription factor MITF." (PMID 27852308, 2016). "Notably, the MITF and GLI2 genes are inversely expressed in various melanoma cell lines." (PMID 27941997, 2016). "Furthermore, our previous demonstration of PLK-1 as a potential therapeutic target in melanoma, together with the ability of PLK-1 inhibition to override MITF-mediated intrinsic resistance suggest mitotic kinases as potential avenues for therapeutic intervention in melanoma." (PMID 26962685, 2016). "discover PAX3-mediated overexpression of MITF as a reversible resistance mechanism to MAPK-pathway inhibition in BRAF mutant melanomas and identify nelfinavir, which inhibits this mechanism and sensitizes not only BRAF mutant but also BRAF and NRAS mutant melanoma cells to MAPK-pathway inhibitors." (PMID 26977879, 2016). "Moreover, even in cells that do not display elevated expression of MITF, its relevance for melanoma cell survival appears to be sufficient for inhibitor sensitization." (PMID 26977879, 2016). "As targeting NF-κB enhances response to RAF inhibitors and targeting MITF along with HDAC prevents cAMP/MITF-driven resistance to MAPK-pathway inhibitors, PN might be considered as a part of combined therapy for melanoma patients with BRAFV600E-driven melanomas." (PMID 26824319, 2016). "Interestingly, although MITF knockdown by itself failed to bear any significant impact on melanoma cell viability, its combination with AURKA-i greatly potentiated the latter's anti-proliferative activity." (PMID 26962685, 2016). "In summary, we have in this study shown that MITF depletion results in elevated expression levels of both the ERBB3 receptor and its cognate ligand NRG1-beta, which may have potential implications for acquired drug resistance in melanoma." (PMID 27391157, 2016). "Furthermore, existence of the cell population that has MITF-Mhigh/NF-κBhigh phenotype (DMBC21) indicates that NF-κB not always antagonizes MITF expression in BRAFV600E-mutant melanomas." (PMID 26824319, 2016). "These subpopulations of ‘MITF‐negative’ cells, which are contained within a subset of melanoma cell populations originally identified by Hoek and colleagues, are characterized by the expression of the non‐canonical Wnt ligand WNT5A and the receptor tyrosine kinase AXL." (PMID 25818589, 2015). "However, in a recent study involving targeted-capture deep sequencing, no copy gains at the MITF locus have been found in a panel of melanoma metastases." (PMID 25433395, 2015). "These somatic mutations, however, do not affect the DNA-binding ability of MITF in melanoma cells." (PMID 25433395, 2015).
melanoma (continued). "In this context, it is striking that ~14% of melanomas stain positive for MITF and AXL, but it is not clear, whether in these tumours, cells have undergone partial switching." (PMID 25818589, 2015). "Several transcription factors and signaling pathways involved in the regulation of MITF expression and/or activity such as the Wnt/β-catenin pathway are broadly utilized by various types of tumors, whereas others, e.g., BRAFV600E/ERK1/2 are more specific for melanoma." (PMID 25433395, 2015). "We hypothesise that the role of CITED1 in melanoma is to maintain levels of MITF compatible with tumour progression and effectively tip the balance in favour of cell cycle progression rather than MITF-induced G1-arrest." (PMID 25755924, 2015). "However, even without drug targeting, induction of MITF, to levels seen in melanocytes or above what is tolerated by even the highly pigmented tumour cell types, would seem to be incompatible with melanoma progression as it can inhibit cell cycle progression." (PMID 25755924, 2015). "Curiously enough, we could find that A431 (a non melanoma cell line) having comparatively low or nil expression of Brn-2 and MITF, and perhaps not depending on these molecules for its survival, was relatively non-sensitive to DW-F5 (IC50- 47.1 μg/ml)." (PMID 26061820, 2015). "In their subsequent studies the authors used gain-of-function and loss-of-function approaches to demonstrate that MITF is capable of cooperating with mutant BRAF to transform normal cells and that MITF knockdown causes loss of viability in MITF copy-gain melanoma cells." (PMID 24904423, 2014). "Progression of melanoma is associated with decreased differentiation and lower expression of MITF although its function may not be the same in melanoma as in normal melanocytes." (PMID 24587106, 2014). "LXRs are upregulated in melanocytes from perilesional skin of vitiligo patients, and LXR activation could inhibit the melanogenesis in human primary melanocytes and murine B16 melanoma cells by downregulating melanogenic enzymes through Ras- and ERK-induced MITF degradation." (PMID 24564864, 2014). "Besides the effects of ZEB2 expression on MITF and cellular plasticity, ZEB2 might also have a tumor-suppressive role due to its modulation of PTEN in a complex RNA-regulatory network in melanoma." (PMID 25538895, 2014). "Moreover, hypoxic conditions increase the tumorigenic potential of melanoma cells whereas pharmacological depletion of a MITF-negative population by forskolin treatment inhibits tumor and metastasis development." (PMID 25538895, 2014). "In addition, apoptosis, label-retention, frequency of ABCB5-positive cells and the expression of Wnt/β-catenin signaling target genes, MITF and c-MYC, were assessed in melanoma populations treated with compounds selected as either highly anti-clonogenic or highly cytotoxic." (PMID 24595456, 2014). "The immunohistochemical marker MiTF also may contribute to this differential, as it is frequently positive in melanoma, clear cell sarcoma, and PEComa, but is typically negative in melanotic Xp11 TRC." (PMID 24735727, 2014). "In melanoma, AXL is activated and preferentially expressed in melanoma lacking MITF." (PMID 24344100, 2013). "However, the mechanisms that establish and maintain the precise chromatin conformation required for MITF to activate specific target genes in melanoma cells were not previously known." (PMID 23480510, 2013). "Dinaciclib targeted melanoma cell lines regardless of cdk2 or MITF levels." (PMID 23527225, 2013). "Thus, in melanoma, BRG1 and MITF activate ML-IAP, independently of BAF180." (PMID 23480510, 2013). "Moreover, we showed previously that PAX3 does not regulate MITF in melanoma cells and we now propose a “genetic switch” theory to explain phenotype switching, whereby a PAX3-POU3F2 axis and a MITF-miR-211 axis function to negatively regulate each other." (PMID 24062982, 2013).
melanoma (continued). "Although the requirement for MITF has been investigated in melanoma cells, it is not known whether MITF regulates ML-IAP expression in non-tumorigenic cells." (PMID 23480510, 2013). "We reported previously that PAX3 is extensively expressed in melanocytes, nevi and melanoma tissues, and that expression levels of PAX3 and MITF are highly variable in melanoma cell lines, and are not concordant with each other, especially comparing individual melanoma cells in culture." (PMID 24062982, 2013). "Although both BRG1 and BRM display extensive homology and are interchangeable in function to support MITF and its targets expression in melanoma, their function in SWI/SNF complexes may not be equivalent." (PMID 23349796, 2013). "Therefore, simultaneous inhibition of MITF and BCL2 may be especially potent by sensitizing melanoma cells to apoptosis." (PMID 22927992, 2012). "We find that the experimentally observed crosstalk between MITF and STAT3 via PIAS3 in melanocytes is faithfully reproduced in our model, offering mechanistic explanations for this behaviour, as well as providing a scaffold for further studies of MITF signalling in melanoma." (PMID 22316093, 2012). "Moreover, in some melanoma cells it was noted a variable nucleotide tandem repeat (VNTR) in the pri-miRNA-137 that alters the function of mature miR-137 and hinders this miRNA to promote MITF repression." (PMID 21860617, 2012). "However, the striking finding was that TYR and MITF transcripts were not detectable in patients with melanomas." (PMID 22829910, 2012). "MITF targeting Dicer in melanocytes may partially explain our findings of up-regulated Dicer in melanoma and not carcinoma or sarcoma." (PMID 21698147, 2011). "In order to determine whether JunB lost its ability to elicit negative regulation of SOX10 and MITF in melanoma cells where ATF2 no longer inhibited SOX10 or MITF expression, we transfected those cell lines with TAM67 and JunB alone and in combination." (PMID 21203491, 2010). "In two out of the 12 melanoma lines ATF2 affected SOX10 but not MITF transcription." (PMID 21203491, 2010). "The retention of MITF expression in the vast majority of human primary melanomas, including non-pigmented tumors, is consistent with this hypothesis and has also led to the widespread use of MITF as a diagnostic tool in this malignancy." (PMID 19828018, 2009). "This suggests that the MITF promoter is regulated differently by oncogenic BRAF in mouse and human cells, but it should be mentioned that in contrast to humans, somatic mutations in BRAF do not appear to be a feature of mouse melanomas." (PMID 18628967, 2008). "Importantly, we show that wild type BRAF does not induce BRN2 expression in melanocytes, and neither does it stimulate MITF transcription in melanocytes or melanoma cells." (PMID 18628967, 2008). "Moreover, using the CZECANCA NGS panel, we mainly tested genes established in predisposition to solid tumors including some, but not all genes known to predispose to RCC such as MITF, which was not included in our panel, but its GPV have been reported in patients with melanoma and RCC." (PMID 39777909, 2025). "Likewise, while many stress responses in melanoma cells were associated with high NGFR and low MITF expression, other stress and invasiveness-inducing conditions resulted in increased NGFR levels but without affecting MITF expression." (PMID 36638181, 2023). "This may be a negative feedback mechanism that attenuates oncogenic MITF signaling in melanomas." (PMID 36901857, 2023). "However, to study this in vitro is challenging, as was noted by us and many other groups: melanocytes and melanoma cells do not tolerate strong modulations of the expression levels of MITF whether by depletion or overexpression." (PMID 36812891, 2023).